SCARNA13 (small Cajal body-specific RNA 13)
Synonyms: U93
Gene: Small Cajal body-specific RNA gene on chromosome 14 (95,533,355 to 95,533,629, reverse strand). Ensembl gene ENSG00000252481.
Gene Ontology:
Biological process: RNA processing
Cellular component: Cajal body; nucleolus
Homologues: Orthologues: chimpanzee SCARNA13 (99% identical), macaque SCARNA13 (97% identical), guinea pig SCARNA13 (88% identical).
Diseases named in the same sentence as SCARNA13 in open-access papers:
SCARNA13 is named in the same sentence as 3 diseases in open-access papers, as found by Europe PMC text mining. Sharing a sentence is not in itself a finding about the gene and the disease. The quoted sentences say what the papers report.
liver cancer (1 paper, 2020). An epithelial or non-epithelial malignant neoplasm that arises from the liver. "It is reported that SNHG10 was upregulated in liver cancer and formed a positive feedback loop with its homolog SCARNA13, thereby promoting cancer metastasis." (PMID 33081752, 2020).
cancer (2 papers, 2020 to 2021). A tumor composed of atypical neoplastic, often pleomorphic cells that invade other tissues. "As novel drivers of the malignant phenotype of HCC, SNHG10 and its homolog SCARNA13, which form a positive feedback loop, coordinately contribute to the cancer development." (PMID 34257164, 2021).
tumor (1 paper, 2022). "In addition, SNHG10 regulates the expression of its homolog SCARNA13 to promote tumor metastasis." (PMID 35506202, 2022).